HELLS (helicase, lymphoid specific)
Diseases named in the same sentence as HELLS in open-access papers (continued):
Sharing a sentence is not in itself a finding about the gene and the disease.
retinoblastoma (continued). "In this study, we also sought to determine whether HELLS plays a critical role during retinoblastoma development." (PMID 32071286, 2020). "Transcriptional activation of HELLS by E2F1 in retinoblastoma, gliomas, and in cell lines has been reported while in skin stem cells HELLS has been reported to be a target of an isoform of p63, but there are no previous reports of HELLS regulation in medulloblastoma." (PMID 31541170, 2019). "Multiple studies have shown that HELLS knockdown in vitro results in decreased proliferation of various cancer cell types including retinoblastoma, gliomas, nasopharyngeal and breast cancer cells, and that engraftment of cells carrying ectopically expressed HELLS gives rise to heavier tumor burden." (PMID 30220967, 2018). "In addition to retinoblastoma, several reports have shown that HELLS overexpression contributes to malignant progression including renal cell carcinoma, gliomas, prostate cancer, melanoma, and nasopharyngeal carcinoma." (PMID 30220967, 2018). "In retinoblastoma, HELLS was identified as a critical contributor of Rb-mediated tumorigenesis." (PMID 30220967, 2018). "Taken together, these data suggest that targeting HELLS may be an effective treatment strategy in retinoblastoma or an alternative approach to identifying novel therapeutic targets." (PMID 25338120, 2014). "To determine whether UHRF1 or HELLS expression are required for retinoblastoma’s growth, survival, or both, we acquired lentiviral vectors encoding shRNAs to UHRF1 (lenti-UHRF1) and HELLS (lenti-HELLS)." (PMID 25338120, 2014). "Like UHRF1, HELLS was also epigenetically upregulated in human retinoblastoma." (PMID 25338120, 2014). "At the protein level, we identified overexpression of UHRF1 and HELLS in a subset of the human retinoblastoma tumors and in all the human retinoblastoma cell lines analyzed (RB355, Weri, and Y79) when compared to normal fetal retina (FW19) and normal human fibroblasts (BJ)." (PMID 25338120, 2014). "Indeed, qPCR analysis of primary human retinoblastoma tissue showed that UHRF1 and HELLS are significantly upregulated in some retinoblastomas." (PMID 25338120, 2014). "Interestingly, researching the data from our previous integrative analysis of human retinoblastoma, we found that the human orthologs, UHRF1 and HELLS, were both epigenetically upregulated in human retinoblastoma." (PMID 25338120, 2014). "Together, these data suggest that HELLS overexpression (or persistent expression) may contribute to the maintenance of a de-differentiated and proliferative state in Rb1/p107-null retinae that may result in retinoblastoma formation." (PMID 32071286, 2020). "HELLS (helicase, lymphoid specific; also known as LSH, ICF4, PASG, and SMARCA6), a gene transcriptionally controlled by the RB/E2F pathway, encodes a chromatin remodeling protein thought to be responsible for the epigenetic changes seen in retinoblastoma and required for tumor survival." (PMID 32071286, 2020). "We also found that Uhrf1 (ubiquitin-like, containing PHD and RING finger domains 1) and Hells (helicase, lymphoid specific) proteins are overexpressed in retinoblastoma and may be responsible for the epigenetic changes seen in retinoblastoma and required for tumor survival." (PMID 25338120, 2014). "Transcriptome analysis of RB1 knockout organoids and primary retinoblastoma revealed gain of a retinoblastoma expression signature in the organoids, characterized by upregulation of RBL1 (p107), MDM2, DEK, SYK and HELLS." (PMID 35565295, 2022). "We verified that HELLS overexpression occurs soon after tumor initiation in Chx10-Cre Rb1lox/lox p107−/− (Rb1/p107 DKO) retinae and this overexpression persists in retinoblastoma tumors." (PMID 32071286, 2020).
Immunodeficiency (12 papers, 2017 to 2026). Failure of the immune system to protect the body adequately from infection, due to the absence or insufficiency of some component process or substance. "For instance, mutations in HELLS gene result in immunodeficiency, centromeric instability, and facial anomalies." (PMID 41569154, 2026). "Aberrant expression and function of HELLS are associated with various diseases, including cancer and immunodeficiency disorders." (PMID 41569154, 2026). "Mutations in the HELLS gene have been reported to be associated with the human immunodeficiency syndrome ICF (immunodeficiency, centromeric instability, facial anomalies)." (PMID 40342810, 2025). "Mutation of HELLS (Helicase, Lymphoid-Specific)/Lsh in human DNA causes a severe immunodeficiency syndrome, but the nature of the defect remains unknown." (PMID 32727902, 2020). "Mutations of the SNF2 family ATPase HELLS and its activator CDCA7 cause immunodeficiency, centromeric instability, and facial anomalies syndrome, characterized by DNA hypomethylation at heterochromatin." (PMID 39178260, 2024). "Immunodeficiency, centromeric instability, and facial anomalies syndrome (ICF) is a rare genetic defect that is inherited in an autosomal recessive manner, and the pathogenic genes include DNMT3B, ZBTB24, CDCA7, and HELLS." (PMID 39958354, 2025). "Immunodeficiency, centromeric instability, facial anomalies (ICF) syndrome is a rare autosomal recessive disorder that is caused by mutations in either DNMT3B, ZBTB24, CDCA7, HELLS, or yet unidentified gene(s)." (PMID 33082427, 2020). "In addition, recent studies have highlighted a role for ZBTB24, CDCA7 and HELLS in Non-homologous end joining (NHEJ), a pathway involved in DNA repair but also in immunoglobulin class-switch recombination, linking LoF of ICF factors to immunodeficiency that affects most of ICF patients." (PMID 33916664, 2021).
pancreatic cancer (9 papers, 2021 to 2023). "HELLS plays oncogenic roles in the development and progression of pancreatic cancer and serves as a biomarker of poor prognosis for pancreatic cancer." (PMID 36012581, 2022). "HELLS is upregulated in clinical pancreatic cancer tissues, and its upregulation also correlates with advanced clinical stage and poor prognosis." (PMID 36012581, 2022). "Results revealed that the mRNA levels of SMARCA3, SMARCA4, HELLS were significantly upregulated in patients with pancreatic cancer, while the mRNA levels of SMARCA2 and SMARCAD1 were downregulated." (PMID 34315468, 2021). "Consistently, significantly higher mRNA and protein expressions of HELLS were observed in pancreatic cancer tissues compared to normal tissues." (PMID 34315468, 2021). "To determine the oncogenic roles of HELLS in pancreatic cancer, we stably knocked down HELLS in PANC-1 cells, and verified at mRNA and protein levels." (PMID 34315468, 2021). "In Pei’s dataset, HELLS was overexpressed in pancreatic cancer with a fold change of 2.386 and a P value of 3.50E−8." (PMID 34315468, 2021). "We found that pancreatic cancer highly expressed a chromatin remodeler, HELLS, and downregulation of it led to decreased growth of pancreatic cancer and improved sensitivity to cisplatin." (PMID 33280236, 2021). "The statistical data showed a significant increase in S fraction in shHELLS group compared with the shHELLS-con group (****P = 0.0001), indicating that knockdown of HELLS inhibited cell proliferation by arresting cells at S phase in pancreatic cancer." (PMID 34315468, 2021). "Hou revealed that HELLS might serve as an oncogene in pancreatic cancer, and downregulating HELLS impaired tumor growth." (PMID 35912252, 2022). "Remarkably, downregulation of HELLS reverses the malignant phenotype in pancreatic cancer." (PMID 36012581, 2022). "Moreover, HELLS knockdown leads to cell cycle arrest and enhanced cisplatin sensitivity of pancreatic cancer cells." (PMID 34944699, 2021). "In addition, downregulation of HELLS inhibits pancreatic cancer cells proliferation and colony formation, and induces cell cycle arrest in vitro." (PMID 34315468, 2021). "However, in pancreatic cancer, Hou found that HELLS is upregulated; downregulation leads to tumor growth arrest and increased sensitivity to cisplatin." (PMID 35087751, 2021). "Notably, among the SMARCA family members, data mining analysis showed that mRNA and protein levels of HELLS are negatively correlated with outcomes in pancreatic cancer patients, which is highly in accordance with its oncogenic roles in previous literature." (PMID 34315468, 2021). "Mechanistically, HELLS overexpression inhibited transcriptional expression of the tumor suppressor TGFBR3 in this model, and downregulation of HELLS in pancreatic cancer cells led to re-expression of TGFBR3." (PMID 36012581, 2022). "Moreover, lymphocyte-specific HELLS, a SWI2/SNF2 chromatin remodeling enzyme, is upregulated in pancreatic cancer tissues and correlates with an advanced clinical stage and poor prognosis." (PMID 36304446, 2022).
glioblastoma (7 papers, 2020 to 2026). The most malignant astrocytic tumor (WHO grade IV). "HELLS, lymphoid-specific helicase gene, is associated with gene repair as well as chromosomal stability, and high expression of the HELLS gene is associated with glioblastoma progression and poor prognosis." (PMID 41438689, 2026). "Significant upregulation of HELLS has been reported in 33 human cancer types, including breast, leukemia, and glioblastoma." (PMID 41297801, 2025). "Targeted inhibition of HELLS by shRNA in an orthotopic xenograft model resulted in improved survival and decreased glioblastoma tumor growth." (PMID 36012581, 2022). "Both E2F3a and E2F3b were found to interact with HELLS, thereby increasing the expression of cell cycle progression-related genes to maintain glioblastoma CSC proliferation, while proliferation was impaired after E2F3 gene knockdown." (PMID 34476219, 2021). "The clinical significance of HELLS in glioblastoma is highlighted by the poor prognosis of glioblastoma patients with elevated HELLS expression and the improved survival of glioblastoma mouse models upon HELLS downregulation." (PMID 41297801, 2025). "In glioma, HELLS regulates the proliferation of stem cell-like glioblastoma stem cells by interacting with key oncogenic TFs E2F3 and MYC; targeted the inhibition of HELLS and prolonged survival in mice and improved the prognosis of patients with increased HELLS expression." (PMID 35774795, 2022). "Additionally, glioblastoma CSCs display the dependence of HELLS (helicase, lymphoid-specific) to maintain proliferation." (PMID 34476219, 2021).
glioma (7 papers, 2018 to 2022). A benign or malignant brain and spinal cord tumor that arises from glial cells (astrocytes, oligodendrocytes, ependymal cells). "In recent years, the chromatin remodeling protein HELLS has been increasingly considered as a therapeutic target in several cancers, including gliomas and carcinomas." (PMID 32071286, 2020).
nasopharyngeal carcinoma (7 papers, 2014 to 2022). A carcinoma arising from the nasopharyngeal epithelium. "HELLS has also been implicated in nasopharyngeal carcinoma (NPC)." (PMID 36012581, 2022). "The expression of HELLS is significantly elevated in the advanced clinical stage of nasopharyngeal carcinoma compared with that in the early stage." (PMID 33280236, 2021). "In nasopharyngeal carcinoma, HELLS upregulation was observed in cancerous tissues to positively correlate with advanced clinical stage and recruitment of the key epigenetic regulator G9a to suppress the activity of fumarate hydratase and drive cancer progression." (PMID 33280236, 2021). "HELLS is overexpressed in many human tumors and has been shown to hinder cell cycle re-entry and cellular growth whereas NOLC1 expression is crucial for the growth of nasopharyngeal carcinomas." (PMID 24892549, 2014).
breast carcinoma (6 papers, 2009 to 2022). "HELLS has been implicated in leukaemia, non-small cell lung cancer, breast cancer, and melanoma." (PMID 19287496, 2009). "Experimental studies have shown that CDKN2A, PSAT1, HMGB1, ELAVL1, and SLC7A11 were up-regulated in TNBC, ASNS and LAMP2 were up-regulated in breast cancer and CAV1 was down-regulated in breast cancer, and HELLS was up-regulated in other tumors." (PMID 36568247, 2022). "HELLS expression was also elevated in breast cancer, non-smallcell lung cancer, and liver cancer." (PMID 35774795, 2022). "In addition, the possible ferroptosis mechanisms of CDKN2A, PSAT1, SLC7A11, LAMP2, CAV1, and HMGB1 in TNBC and ASNS, ZFP69B, ELAVL1, TF, HELLS, and DPP4 in breast cancer have not been reported." (PMID 36568247, 2022).
non-small cell lung carcinoma (6 papers, 2009 to 2021). A group of at least three distinct histological types of lung cancer, including non-small cell squamous cell carcinoma, adenocarcinoma, and large cell carcinoma. "Although a HELLS splicing variant has been described in non-small cell lung cancer, The Cancer Genome Atlas (TCGA) data shows a very low frequency for HELLS mutations in CRC." (PMID 31867127, 2017). "HELLS has been implicated in the progression in non-small cell lung carcinoma and squamous cell carcinoma in the head and neck region." (PMID 27191985, 2016). "HELLS gene known as lymphoid-specific helicase (LSH), which encodes a lymphoid-specific helicase, may be involved with cellular proliferation and may play a role in the development of non-small cell lung carcinoma." (PMID 29285211, 2017).
cervical carcinoma (5 papers, 2022 to 2025). A carcinoma arising from either the exocervical squamous epithelium or the endocervical glandular epithelium. "Elevated HELLS expression was observed in cervical cancer, and its overexpression was associated with increased cell viability and colony formation while inhibiting cell death induced by ferroptosis." (PMID 38047020, 2023). "HELLS was overexpressed in cervical cancer and promoted the proliferation of cervical cancer by regulating the expression of nuclear factor erythroid 2-related factor 2 (Nrf2)." (PMID 39944833, 2025). "Mechanistically, HELLS was found to promote cervical cancer proliferation through the regulation of Nrf2-mediated ferroptosis." (PMID 38047020, 2023). "Xing reported that HELLS expression levels were correlated with the OS of cervical carcinoma and endocervical adenocarcinoma." (PMID 35912252, 2022). "In cervical cancer, HELLS promotes tumor cell proliferation by repressing NRF2 expression, suggesting that targeting HELLS could restore ferroptosis sensitivity." (PMID 40895556, 2025). "The downregulation of HELLS has been demonstrated to inhibit tumor cell proliferation, colony formation, and induce G2/M cell cycle arrest, thereby representing a potential effective treatment for cervical cancer." (PMID 39944833, 2025). "In addition, the expression of four genes, including JUN, TSC22D3, DUOX1, and HELLS, in cervical cancer tissues was verified by qRT-PCR." (PMID 37187896, 2023). "In the current study, we clarify the function of HELLS in cervical cancer progression." (PMID 38047020, 2023). "In this study, we investigated the role of lymphoid-specific helicase (HELLS) in cervical cancer." (PMID 38047020, 2023). "However, the function of HELLS in the development of cervical carcinoma is still unclear." (PMID 38047020, 2023). "Therefore, HELLS knockdown may be an effective treatment for cervical cancer." (PMID 38047020, 2023).
colorectal cancer (5 papers, 2021 to 2023). A primary or metastatic malignant neoplasm that affects the colon or rectum. "Downregulation of HELLS in colorectal cancer cells led to decreased cell proliferation, colony formation, and G2/M cell cycle arrest." (PMID 36012581, 2022). "Our previous work found that the inhibition of HELLS leads to cell cycle arrest in colorectal cancer." (PMID 33280236, 2021). "Our previous study demonstrated that HELLS is overexpressed in colorectal cancer and promotes tumor growth." (PMID 33280236, 2021). "HELLS is significantly overexpressed in clinical samples of colorectal cancer." (PMID 36012581, 2022). "In addition, NOLC1 may be associated with MCM10, HELLS, NOC3L, and other genes through participating in Wnt signaling pathways and jointly regulate the occurrence and development of colorectal cancer under the influence of the tumor microenvironment and many other influencing factors." (PMID 37670166, 2023). "Therefore, we hypothesized that NOLC1 plays an indispensable role in the regulation of the occurrence and development of colorectal cancer, and it may promote the invasion and metastasis of colorectal cancer together with MCM10, HELLS, and Noc3L-related genes." (PMID 37670166, 2023).
melanoma (5 papers, 2007 to 2022). A malignant, usually aggressive tumor composed of atypical, neoplastic melanocytes. "In human melanoma, elevated levels of HELLS were associated with tumor progression, and HELLS has been identified as a valid biomarker in liquid biopsies with superior prognostic value compared with LDH." (PMID 32466590, 2020). "Like 2A-DUB/MYSM1, the newly-identified MYSM1 interaction partners, HELLS and RFC4/5, have also been implicated in tumorigenesis, specifically in melanoma growth; HELLS is frequently misregulated in a variety of cancers." (PMID 32466590, 2020). "Notably, HELLS overexpression is associated with progression of squamous cell, oropharyngeal and prostate cancers, with high HELLS levels also found in bladder, retinal, lung and ovarian tumours and HELLS expression a potential biomarker for melanoma metastasis." (PMID 31802118, 2020).
liver cancer (4 papers, 2021 to 2025). An epithelial or non-epithelial malignant neoplasm that arises from the liver. "Overexpressed HELLS is significantly associated with liver cancer and related to poor prognosis in patients." (PMID 33190424, 2021). "Contrary to previous findings, our study showed that HELLS knockdown in liver cancer cell lines resulted in hypermethylation in 89% of the probes analyzed." (PMID 40175344, 2025). "In this study, we identified mitochondrial elongation factor 1 (MIEF1), one of the DRP1 receptors, as a novel oncogene and a direct transcriptional target and critical executor downstream of HELLS in liver cancer." (PMID 40175344, 2025). "Furthermore, overexpression of HELLS increased MIEF1 levels and enhanced colony-forming ability in non-tumorigenic liver cancer." (PMID 40175344, 2025).